VEGFA (vascular endothelial growth factor A)
Diseases named in the same sentence as VEGFA in open-access papers (continued):
Sharing a sentence is not in itself a finding about the gene and the disease.
cancer (continued). "MiR-664a-3p was mainly distributed in the PDAC cancer stroma, including fibers and vessels, and was accompanied by VEGFA expression." (PMID 38035445, 2024). "VEGFA maintains cancer stemness and progression of TNBC through the NRP-1/GAPVD1 axis and Wnt/β-catenin signaling pathway." (PMID 38169627, 2024). "Extracts from various Chinese herbs and plants have also been found to have the potential to inhibit the angiogenesis in various cancers by regulating VEGFA." (PMID 38687357, 2024). "IFI27 has been reported to be involved in the growth of blood vessels by upregulating vascular endothelial growth factor-A (VEGF-A) in cancer cells." (PMID 39070493, 2024). "Considering the important role of VEGFA in chemotherapy or targeted drug resistance, especially in regulating cancer stem cells, the combination of bevacizumab is also very attractive for preventing the development of drug resistance." (PMID 38716237, 2024). "We analyzed the human‐specific and mouse‐specific mRNAs differentially expressed after BRAF/VEGFA targeting in order to identify intercellular signals between cancer and stromal cells." (PMID 37183363, 2023). "SFN also inhibited cancer cell invasion and decreased the expression of pro-angiogenic markers (VEGFA, VEGFR2, HIF-1α, and eNOS) in both iCCA cell lines." (PMID 36899823, 2023). "VEGFA is a pivotal regulator of vascular development such as angiogenesis, which is an important process in cancer development." (PMID 37234708, 2023). "The GSEA results proved that asparagine N-linked glycosylation, pathways in cancer, G alpha (i) signalling events, PI3K-Akt pathway, VEGFA-VEGFR2 and other pathways were significantly gathered in GC patients of the high-risk groups." (PMID 37036489, 2023). "By binding to VEGFR2 and mediating multiple signaling pathways, VEGFA stimulates angiogenesis and promotes cancer progression in multiple cancers." (PMID 38204755, 2023). "VEGFA promotes cancer cell renewal, cell migration, invasion and metastasis through induction of SOX-2, which in turn activates SNAI2, an EMT transcription factor." (PMID 37173939, 2023). "Conversely, when compared to OATL4, the response pathways of ED40515 were notably centered around transcriptional misregulation in cancer and VEGFA-VEGFR2 signaling (Supplementary 17C)." (PMID 38344143, 2023). "For example, targeting endothelial- and tumor-derived vascular endothelial growth factor A (VEGF-A) signaling agents have been investigated as potential cancer drugs." (PMID 35895109, 2023). "To date, both SDF-1α/CXCR4 and VEGFA/VEGFRs pathways are the principal mediators of BM-derived EPC mobilization during cancer development and represent potential targets for novel anti-vasculogenic therapies." (PMID 36983398, 2023). "Most circRNAs upregulate VEGFA expression, and high levels of VEGFA exacerbate the symptoms of various cancers." (PMID 37234708, 2023). "LYZ is associated with neutrophil degranulation and host defense peptides, whereas COL1A1, COL1A2 along with HGF, TNC, and VEGFA are all part of the PI3K pathway, which plays an important role in cancer progression, and has been implicated in TNT regulation." (PMID 37955637, 2023). "It was found that HUVEC cells cultured with cultures of si-NUPR1-transfected cancer cells showed a significant reduction in tube formation activity and inhibition of VEGFA expression." (PMID 37854285, 2023). "We discovered that MDM2, PTGS2, EGFR, and VEGFA are the key genes regulated by JCF and closely associated with the development of cancer." (PMID 37361218, 2023). "Guided by the biological function of VEGFA and the expansive role of circRNAs, many findings have demonstrated the regulatory pathways that circRNAs participate in cancer pathogenesis through modulating VEGFA activities." (PMID 37234708, 2023).
cancer (continued). "During cancer progression, upregulation of multiple pro-angiogenic factors, such as vascular endothelial growth factor A (VEGFA), PDGF, and IGF-1, and downregulation of anti-angiogenic factors, such as ENS and PF-4, contributes to pathological angiogenesis." (PMID 36720310, 2023). "It is reasonable to assume that a partially reduced expression of VEGFA in a solid cancer will result in a reduction or delay in angiogenesis and thereby a decrease in cancer growth." (PMID 37998393, 2023). "VEGFA is expressed in almost all types of malignant tumors and is currently still an important target for anti-angiogenesis drugs targeting tumors." (PMID 36641437, 2023). "In this review, we will summarize the origin and functional mechanisms of VEGFA and circRNAs, and explore the role of circRNAs in cancer pathogenesis through the regulation of VEGFA." (PMID 37234708, 2023). "The starBase database in Pan-Cancer shows that miR-126-5p correlates with VEGFA in the miRNA-target co-expression field." (PMID 37020848, 2023). "VEGFA, a key mediator of angiogenesis in cancer, was found to be one of the 12 prognosis-related genes." (PMID 37741941, 2023). "In this paper, we explored the origin and functional pathways of VEGFA, reviewed the current understanding of circRNA properties and action mechanisms, and summarized the role of circRNAs in regulating VEGFA during cancer pathogenesis." (PMID 37234708, 2023). "IHC of proliferative, cancer specific, vascular targeting, inflammatory molecules, including c-Met, Ki-67, VEGFA, cluster of differentiation 31 (CD31), and iNOS, were scored based on an inspection by a pathologist and relevant references." (PMID 37228164, 2023). "Emerging studies have uncovered that VEGFA mediated autophagy to regulate the biological functions of various cells, such as granulosa cells, cancer cells, endothelial cells, and so on." (PMID 37226251, 2023). "Gene expression analyses provided insights into the molecular mechanisms underlying AV25R’s effects, revealing a multitude of differentially expressed genes and significant regulation of cancer-related pathways such as VEGFA-VEGFR2 and EGF/EGFR." (PMID 38138609, 2023). "VEGFA related signal transduction plays a crucial role in the migration of cancer cells from their primary niche to their secondary sites." (PMID 36830681, 2023). "Under the hypoxic condition, TAMs produce angiogenesis-promoting cytokines, chemokines, and growth factors, like vascular endothelial growth factor A (VEGF-A), a well-known factor for vascularization and immunosuppression in multiple cancers, including GBM." (PMID 37731483, 2023). "Here, we reported that BRAF/VEGFA targeting influenced monocyte‐derived macrophages infiltration through a cancer‐derived signal." (PMID 37183363, 2023). "Another example is vascular endothelial growth factor A (VEGF‐A), a well‐known secreted regulator of angiogenesis with important roles in development, tissue growth, and cancer." (PMID 36100972, 2023). "The VEGFA-VEGFR2 signaling pathway and associated angiogenesis, among the seminal hallmarks of cancer, were highlighted as the most overly enriched biologic process (p < 5.0 × 10−7)." (PMID 37895248, 2023). "Reduction in DVL2 function via shRNA resulted in reduced mRNA expression of CCND1 and VEGFA, genes which are involved in cancer cell proliferation and angiogenesis respectively in both SKBR3 and BT474 cells (p < 0.05)." (PMID 36809986, 2023). "VEGFA, a protein with vascular activity, was first extracted from a fluid released by a malignant tumor." (PMID 37571296, 2023). "Previous studies show that VEGFA is highly expressed in tumors and enhances glycolysis in cancer cells with HIF-1α upregulation." (PMID 37737265, 2023). "Multiple studies have shown that VEGFA positively regulates Wnt/β-catenin signaling through β-catenin, which is associated with angiogenesis and cancer stemness in CRC, thus suggesting the potential autocrine action of VEGFA." (PMID 36672201, 2023).
cancer (continued). "Like in the case of VEGFA, the inhibition of TGFβ signaling is currently under evaluation in multiple clinical trials to enhance the efficacy of cancer immunotherapies." (PMID 36418472, 2023). "VEGFA is a critical modulator of angiogenesis, and it has been shown in the literature that VEGFA expression is high in cancer tissue, and this is correlated with its aggressive characteristics." (PMID 37671046, 2023). "The study of gene expression has also established ten hub proteins which significantly contribute to FI and cancer progression; among them VEGFA and PIK3R1 are the most significant for disease progressions." (PMID 36608061, 2023). "Results of Western blot and enzyme-linked immunosorbent assay (ELISA) analysis revealed that overexpression of STK24 promotes secretion of VEGFA by cancer cells, whereas the loss of STK24 decreased the secretion of VEGFA by the cells." (PMID 36720310, 2023). "This miRNA improves the chemosensitivity of cancer cells to TAC by suppressing both vascular endothelial growth factor A (VEGFA) and fibroblast growth factor 2 (FGF2)." (PMID 37510280, 2023). "We discovered VEGFA signaling toward cancer cells in all TAM subsets, highlighting its significant proangiogenic significance." (PMID 38044943, 2023). "In preparation for cancer growth and metastasis, glioma cells were found to promote angiogenesis by increasing the expression of endothelial cell pro-angiogenic factor VEGFA via exosome lncRNA CCAT and lncRNA HOTAIR." (PMID 37007117, 2023). "Gene expression analysis identified a large number of differentially expressed genes after AV25R exposure and significant differentially regulated cancer-related signaling pathways, such as VEGFA-VEGFR2 signaling and the EGF/EGFR pathway." (PMID 38138609, 2023). "Conversely, when compared to OATL4, the response pathways of ED40515 were notably centered around transcriptional misregulation in cancer and VEGFA-VEGFR2 signaling (Supplementary 14C)." (PMID 38344143, 2023). "VEGFA plays a critical role in cancer by promoting the proliferation, angiogenesis and metastasis of cancer cells." (PMID 36982218, 2023). "Vascular endothelial growth factor A (VEGFA) was proved to exacerbate OS and contribute to cancer progression." (PMID 35081965, 2022). "In this process, fibronectin and collagen I were remodeled by upregulated integrins in cancer cells, and VEGFA was enriched in remodeled ECM and induced endothelial cell migration and differentiation." (PMID 35982891, 2022). "The regulatory relationship between miR-429 and VEGFA has been demonstrated in a variety of cancers and systemic diseases." (PMID 35992774, 2022). "TAMs enhance cancer angiogenesis through the release of several pro-angiogenic factors such as VEGFA." (PMID 36551845, 2022). "VEGFA-positive signals in both cancer cells and ECs of the rhGDF15-stimulated U373 cell-injected tumors were significantly higher than those in both cancer cells and ECs of the control U373 cell-injected tumors." (PMID 35280749, 2022). "VEGFA serves as critical role in driving the process of angiopoiesis in local low oxygen environment, which has been also identified as the biomarker in cancer development." (PMID 36193503, 2022). "Bevacizumab, a monoclonal antibody that targets vascular endothelial growth factor A (VEGF-A), is an example of targeted anti-cancer medicine used to treat patients with platinum-sensitive malignancies." (PMID 35630066, 2022). "The demethylation of vascular endothelial growth factor A (VEGFA) enhancer in CML promotes the overexpression of cancer signature genes." (PMID 35514959, 2022). "VEGFA post-transcriptional regulation is exerted through numerous mechanisms in cancer cells, such as for example the HuR- and NF90-dependent mRNA stabilization or microRNA-dependent regulation of translation." (PMID 35710947, 2022). "Our results regarding increased VEGFA expression level in malignant tumors compared to controls and benign lesions are supported by other authors." (PMID 36230822, 2022).
cancer (continued). "Mechanistically, si-FLANC reduced STAT3-induced VEGFA expression, inhibiting OS and cancer progression." (PMID 35081965, 2022). "ID4-dependent release of VEGFA from cancer cells indeed induces a paracrine activation of proangiogenic genes, such as for example Granulin, and downregulation of miR-15/107 family members in TAMs14–16." (PMID 35710947, 2022). "Another enriched cancer-related pathway is VEGFA-VEGFR2 Signaling Pathway which was enriched by RAP1A, SH3BGRL3, and ITGB1." (PMID 35176998, 2022). "A major factor stimulating angiogenesis in cancer tumors is vascular endothelial-derived growth factor A (VEGFA)." (PMID 35208994, 2022). "During this process, cancer cells secrete pro-angiogenesis factors, namely VEGFA, and PDGFB, which accelerate their progression." (PMID 35292059, 2022). "It has been shown that the inhibition of epidermal growth factor receptor 2 (HER2) expression leads to reduced expression of vascular endothelial growth factor A (VEGFA), ultimately resulting in lower angiogenesis and anti-cancer effects." (PMID 35267644, 2022). "The VEGFA is responsible for the formation of new blood vessels, which is important for the progression of cancers." (PMID 35922788, 2022). "A previous study reported that TAM-derived VEGFA enhanced vascular permeability, thereby facilitating cancer cell intravasation and metastasis." (PMID 36303162, 2022). "circ-RanGAP1 sponges miR-877-3p upregulate the VEGFA expression, thus promoting cancer cell aggressiveness in GC." (PMID 35685832, 2022). "Further investigation into the role of VEGFA on autophagy and cancer pathology would benefit this growing field of matrix-derived autophagic effectors in the context of cancer." (PMID 34982945, 2022). "In turn, VEGFA expression was significantly higher in malignant tumors compared to control tissues, and there was a difference in VEGFA expression between benign lesions and normal ovarian tissue." (PMID 36230822, 2022). "Knocking down EBV-circLMP2A can inhibit the formation and migration of human umbilical vein endothelial cells (HUVEC), reduce the expression of VEGFA and HIF1α in cancer cells under hypoxia, and further promote angiogenesis." (PMID 35806027, 2022). "VEGFA is associated with prognosis in patients with MIBC and is also thought to increase the metastasis of cancer cells." (PMID 36430344, 2022). "The immune inhibitor CD276 and VEGFA correlated positively with KIF11 in most human cancer types, but VEGFB correlated negatively with KIF11 in most human cancer types." (PMID 36742345, 2022). "This circular transcript participates in cancer‐related critical pathways, such as VEGFA/VEGFR2, MEK/ERK, and NF‐κB pathways." (PMID 35701309, 2022). "Mutations and alterations in the expression of VEGFA, KRAS, and NFE2L2 oncogenes play a key role in cancer initiation and progression." (PMID 35806488, 2022). "Rho has been suggested to be a potential therapeutic target, since Rho and VEGFA crosstalk leads to cancer progression and metastasis." (PMID 35845599, 2022). "The S component samples were enriched with angiogenesis-related interactions, with high expression of VEGFA and FLT1 (encoding VEGFR1) in cancer cells and macrophages, respectively." (PMID 35874770, 2022). "We showed EPAS1 elevated level in controls and VEGFA in malignant tumors, but only in the group with a lower number of comorbidities." (PMID 36230822, 2022). "VEGFA has long been recognized as a potential vascular and proliferative therapeutic target in cancer patients and it has revealed innovative therapeutic approaches in oncology." (PMID 35884419, 2022). "Co-culture induced VEGFA secretion from SNFT cells which also reduced cancer stem cell differentiation in platinum-resistant A2780 cells." (PMID 35884426, 2022). "For the analysis of 24 immune-inhibiting genes, we found that SERPINH1 expression was highly associated with CD276, TGFBI, VEGFA, HAVCR2, IL10, and ADORA2A in most cancers." (PMID 36105106, 2022).
cancer (continued). "It has been shown preclinically that targeting VEGFA activity or its signalling pathway is one of the pharmacological mechanisms of action of traditional Chinese medicines in cancers." (PMID 35464051, 2022). "It is shown that VEGFA, as an oncogene, was upregulated in a variety of cancers, including LUAD, and promotes the initiation, development, and poor prognosis of cancer." (PMID 35646922, 2022). "As a result, one of the pillars of anti-cancer therapy is based on counteracting pro-angiogenic factors such as Vascular Endothelial Growth Factor A (VEGF-A), angiopoietin 2 (Ang-2) and Delta-like Ligand 4 (DLL4)." (PMID 36432631, 2022). "However, cancer-associated fibroblasts (CAFs) which are located within or near tumours may have altered metabolism and function causing them to secrete factors, chemokines, and enzymes such as VEGFA, CXCL12 and MMPs that can promote angiogenesis." (PMID 36045675, 2022). "Angiogenesis inhibitors targeting the vascular endothelial growth factor and relevant receptor (VEGF/VEGFR) represent an established anti-cancer strategy in the management of various solid tumors, either alone or in combination with chemotherapy/immunotherapy." (PMID 36230533, 2022). "We found that expression of HIF1A and EPAS1 was higher in controls and VEGFA higher in patients with malignant tumors." (PMID 36230822, 2022). "The increased expression of KDR and FLT1 complex in cancer cells and macrophages was correlated with upregulated VEGFA signaling in cancer cells in solid areas, suggesting upregulated angiogenesis and vascular reconstitution." (PMID 35874770, 2022). "The downregulation of miR‐29a contributes to cancer progression by stimulating VEGFA/VEGFR2 and the downstream Ras/ERK signaling pathway, leading to increased angiogenic properties and metastatic features." (PMID 35701309, 2022). "Over the past years, HIF1A, EPAS1, and VEGFA have been highlighted to be attractive potential targets for anti-cancer therapies." (PMID 36230822, 2022). "Hypoxia, via HIF-1, stimulates cancer cells to secrete large amounts of vascular endothelial growth factor A (VEGF-A), which binds to its receptor on the surface of ECs." (PMID 35203510, 2022). "Some researches hold that IGF2 participated in the regulation of the cancer cell secretion of VEGF and further impacted the power of VEGFA antibody." (PMID 33582655, 2021). "Even after extravasation, blood vessels remain in contact with cancer cells, up to the point when the vasculature undertakes remodelling and cooption happens or when Vascular Endothelial Growth Factor-A (VEGF-A) tempts angiogenesis." (PMID 34336101, 2021). "VEGFA, a pleiotropic cytokine, has been considered as the indispensable part of angiogenesis, which mainly leads to cancer-related inflammation." (PMID 33441867, 2021). "Modern medicine has found that VEGFA is involved in many angiogenesis-dependent diseases, including cancer and certain types of inflammatory diabetic retinopathy." (PMID 34423029, 2021). "Angiogenesis in cancer can be modulated by alternative splicing of vascular endothelial growth factor A (VEGFA)." (PMID 34771719, 2021). "Epidermal growth factor receptor (EGFR), Insulin-like growth factor -1 receptor (IGF-1R), and Vascular Endothelial Growth Factor -A (VEGF-A) are overexpressed in various human cancers including CRC." (PMID 34638601, 2021). "Infectious events have also been linked with the administration of Be, a monoclonal antibody targeting the vascular endothelial growth factor A and subsequently angiogenesis in cancer patients." (PMID 34080056, 2021).